ROR1 (ROR family WNT receptor 1)
Diseases named in the same sentence as ROR1 in open-access papers (continued):
Sharing a sentence is not in itself a finding about the gene and the disease.
ovarian carcinoma (continued). "Indeed, a recent study reported that in ovarian cancer cells, it was observed the development of a stemness phenotype, mediated by dex upregulation of ROR1." (PMID 35847038, 2022). "Indeed, targeting ROR1 in ovarian cancer increased the efficacy of second mitochondria-derived activator of caspase (SMAC) mimetics and taxanes." (PMID 33445713, 2021). "Indeed, GR signalling has been shown to negatively impact ovarian cancer disease outcomes by promoting ROR-1 induced stemness and inducing taxane resistance, a mainstay of ovarian cancer treatment." (PMID 33916028, 2021). "The relevance of ROR1 and its therapeutic role has been recently explored in ovarian cancer." (PMID 33172431, 2020). "Previous studies in ovarian cancer found ROR1 played a role in the EMT procedure." (PMID 32807831, 2020). "A previous study identified CD24, CD44, CD117, CD133, and ROR1 as ovarian cancer stem cells." (PMID 32035490, 2020). "Ovarian cancer stem cells express the oncoembryonic surface antigen, receptor tyrosine kinase-like orphan receptor 1 (ROR1): this antigen seems to play a role in the migration and invasion and spheroid formation in vitro and tumor engraftment in immunodeficient mice in vivo." (PMID 29389895, 2018). "Moreover, in future studies, we will investigate the potential mechanisms and biological behavior of ROR1 in ovarian cancer in vivo." (PMID 29212222, 2017). "Future studies will determine whether the ROR1-cFab might be a promising candidate for treatment of ROR1-positive ovarian cancer." (PMID 29212222, 2017). "To examine the specificity and selectivity of this antibody, we employed other techniques such as ELISA, affinity analysis, FACS, and immunofluorescence staining to determine the binding capacity of ROR1-cFab to recombinant human ROR1 antigen and ROR1 protein on the surface of ovarian cancer cells." (PMID 29212222, 2017). "Furthermore, we assessed the antitumor activity of this ROR1-cFab in ovarian cancer cells, our in vitro model of preclinical cancer therapy." (PMID 29212222, 2017). "In other malignancies, such as ovarian cancer, ROR1 has been shown to be highly expressed and may serve as a useful therapeutic target." (PMID 29212222, 2017). "However, Ror1 over expression in the parental cell line increased cell invasion, indicating that Ror1 and Ror2 have potential as novel drug targets in metastatic and recurrent ovarian cancer patients." (PMID 28432357, 2017). "In addition, we performed Western blot to determine the level of ROR1 protein in ovarian cancer A2780 and Iose386 cell lines." (PMID 29212222, 2017). "We demonstrated that ROR1-cFab could specifically bind to ROR1 protein and ROR1-positive ovarian cancer A2780 cells." (PMID 29212222, 2017). "We also assessed cytotoxicity against SKOV-3, HOC-7, and HEY ovarian cancer cell lines that express marginally different levels of ROR1 with killing and cytokine release observed against all cell lines but as before, did not observe a correlation between ROR1 expression and cytotoxicity." (PMID 28811962, 2017). "In addition, we conducted a tumor cell Transwell migration assay to further investigate the effect of ROR1-cFab on ovarian cancer cells in vitro." (PMID 29212222, 2017). "Furthermore, CCK8, flow cytometric apoptosis, wound healing, and Transwell migration assays were used to assess antitumor activity of this newly developed anti-ROR1 antibody in ovarian cancer cells." (PMID 29212222, 2017). "Additionally, upregulation of ROR1 has been identified in chemoresistant ovarian cancer cells." (PMID 37241228, 2023). "Interestingly, ROR1 was shown to be enriched in chemoresistant breast and ovarian cancers." (PMID 36557069, 2022). "Importantly, ROR1 expression correlated with poor clinical outcome in ovarian cancers." (PMID 29389895, 2018). "Indeed, targeting ROR1 suppressed both migration and invasion of epithelial ovarian cancer cells." (PMID 29212222, 2017).
ovarian carcinoma (continued). "We also demonstrated that ROR1-cFab was able to specifically inhibit ovarian cancer cell growth and induce apoptosis in ROR1 expressing cells, suggesting that this antibody could be further investigated as an appropriate and promising therapeutic strategy for ROR1-positive human cancers." (PMID 29212222, 2017). "In addition, we also sought to determine the therapeutic potential of targeting these receptors by performing an extensive suite of in vitro experiments, exploring the functional role of ROR2, its sister receptor, ROR1 and putative ligand, Wnt5a in ovarian cancer." (PMID 26515598, 2015). "Thus, the combination of our results here in ovarian cancer and recent others, suggests that in gynaecological cancers both ROR1 and ROR2 may be over expressed, and important for disease progression." (PMID 26515598, 2015). "Beyond hematologic cancers, 22.0405.aF also demonstrated potent activity against ROR1-positive solid tumors, highlighting its translational potential for TNBC, ovarian cancer, and other ROR1-expressing malignancies." (PMID 41479906, 2025). "ROR1 is known to activate signaling pathways through phosphorylation in cancers such as chronic lymphocytic leukemia (CLL) and ovarian cancer, including downstream JAK/STAT effector proteins." (PMID 40427627, 2025). "siRNA silencing of ROR1 and ROR2 and their ligand, WNTA5, in the ovarian cancer cell line OVCAR3 led to decreased malignant cell proliferation, migration, and invasiveness." (PMID 36873868, 2023). "More recently, a study by Caroline Ford’s group used this model to expand on the synergistic role of Wnt receptors ROR1 and ROR2 in early ovarian cancer metastasis, specifically their role in ovarian cancer cell adhesion to the omentum." (PMID 30096959, 2018). "We have confirmed previous findings that ROR1 and ROR2 have a synergistic role in ovarian cancer invasion, and have presented new evidence that they are also important in adherence to omentum, the critical first step in ovarian cancer metastasis." (PMID 29348860, 2017). "Elevated expression of the ROR1 and ROR2 Wnt receptors has been noted in both the tumour and stromal compartments of ovarian cancer patient tissue samples." (PMID 29348860, 2017). "We previously demonstrated that silencing both ROR1 and ROR2 simultaneously significantly inhibited the ability of ovarian cancer cells to proliferate, migrate and invade in vitro." (PMID 29348860, 2017). "ROR1 and ROR2 are upregulated in a chemoresistant model of ovarian cancer and regulate cell migration and invasion through EMT." (PMID 27239958, 2016). "Here we report that ROR1 and ROR2 expression is increased in this chemoresistant cell line and support our initial findings that ROR1 and ROR2 regulate ovarian cancer cell migration and invasion." (PMID 27239958, 2016). "We have shown for the first time that both ROR1 and ROR2 regulate ovarian cancer cell migration and invasion." (PMID 26515598, 2015). "Here we investigated the role of two Wnt receptor tyrosine kinases (RTKs), ROR1 and ROR2, and their putative ligand, Wnt5a, in ovarian cancer." (PMID 26515598, 2015). "Overexpression of tyrosine kinase-like orphan receptor 1 (ROR1) has been documented in B-CLL, mantle cell lymphoma (MCL), breast cancer, B-ALL, lung adenocarcinoma, melanoma and ovarian cancer." (PMID 26173023, 2015). "However, these unique characteristics of ROR1 have not been reported in ovarian cancer, and may be specific in each cell type, as has been reported for ROR1 and EGFR association in lung cancer models." (PMID 26515598, 2015). "It will be important to elucidate the mode in which ROR1 and ROR2 signal in epithelial ovarian cancer." (PMID 26515598, 2015). "Elevated ROR1 expression has been identified as a marker of cancer stemness and EMT in many gynecological malignancies, including fallopian tube epithelial precursor lesions, endometrial cancer, and epithelial ovarian cancers." (PMID 40869147, 2025).
ovarian carcinoma (continued). "Similar observations have been made in ovarian cancer, in which the synthetic glucocorticoid dexamethasone induced ROR1 expression, which correlated with elevated RHOA, YAP/TAZ, and BMI-1 levels in a panel of ovarian cancer cell lines as well as in the primary patient-derived cells." (PMID 33445713, 2021). "In this model, we selected two ovarian cancer cell lines – both ROR1-positive and negative cell lines – allowing us to further explore the specificity and selectivity of ROR1-cFab." (PMID 29212222, 2017). "The combination of ROR1 and ROR2 signalling influences ovarian cancer dissemination to the omentum, however ROR2 may also play a role in stromal activation during metastasis." (PMID 29348860, 2017). "We found that: 1) ROR1-cFab possesses a high affinity and specificity for ROR1 and 2) ROR1-cFab was able to effectively reduce malignant behaviors of ROR1-positive ovarian cancer A2780 cells, but not in ROR1-negative Iose386 cells in vitro." (PMID 29212222, 2017). "Previous studies have demonstrated that ROR1 antibody or knockdown of ROR1 expression can effectively reduce proliferation of various types of cancer cells, such as chronic lymphocytic leukemia (CLL) cells, ovarian cancer cells, and lung adenocarcinoma cells." (PMID 29212222, 2017). "Therefore, ROR1 and ROR2 have the potential as novel drug targets in metastatic and recurrent ovarian cancer patients." (PMID 27239958, 2016). "Moreover, another study on ovarian carcinoma showed that Wnt5a signaling through Ror1 and Ror2 receptors induced EMT and enhanced ovarian cancer cells migration and in trans-well assay." (PMID 27571105, 2016). "ROR1 and ROR2 present as possible targets for novel therapies for the treatment of ovarian cancer." (PMID 27239958, 2016). "In addition, siRNA was used to silence ROR1, ROR2 and Wnt5a individually, and together, in two ovarian cancer cell lines, and the effects on cell proliferation, adhesion, migration and invasion were measured." (PMID 26515598, 2015). "To understand whether ROR1 expression is exclusive to cancer cells, we analyzed the bulk RNA sequencing (RNA-seq) data following sample decomposition of the DECIDER cohort into epithelial ovarian cancer cells and stromal cells." (PMID 37400436, 2023). "According to these observations it was suggested that ROR1, not expressed on adult tissues, could represent a relevant therapeutic target for ovarian cancer treatment." (PMID 29389895, 2018). "Taken together, our current study revealed that ROR1-cFab could effectively reduce malignant behavior of ovarian cancer A2780, but not Iose386 cells, indicating that ROR1 is the in vitro target of ROR1-cFab antibody." (PMID 29212222, 2017). "Therefore, targeting both ROR1 and ROR2 may be a powerful approach to treating ovarian cancer." (PMID 29348860, 2017). "Our findings here are further supported by the fact that Knockdown of either ROR1 or ROR2 alone did not affect cell adhesion to collagen or fibronectin, suggesting that the ROR receptors do not play a major role in regulating ovarian cancer cell adhesion." (PMID 33723319, 2021). "Eleven of twelve ovarian cancer cell lines tested positive for ROR1 (EFO27 and OC314 are shown as examples) and A2780 was the only ovarian cancer cell line we evaluated that did not express ROR1." (PMID 26030772, 2015).
leukemia (46 papers, 2012 to 2025). A malignant (clonal) hematologic disorder, involving hematopoietic stem cells and characterized by the presence of primitive or atypical myeloid or lymphoid cells in the bone marrow and the blood. "High-level leukemia cell expression of ROR1 is associated with a poor prognosis." (PMID 41303291, 2025). "We confirmed that ROR1 encoded a protein that could be detected on the surface of a leukemia-cell line, MEC1." (PMID 39062146, 2024). "Interestingly, recent observations indicate that the pro-survival function of ROR1 not only strongly supports leukemogenesis, but is also linked with the development of leukemia." (PMID 33445713, 2021). "ROR1 acts as a receptor for Wnt5a, which can stimulate ROR1-dependent activation of Rho-GTPases in leukemia cells." (PMID 41303291, 2025). "Using the leukemia cells from each of these transgenic mice we examined for MMP-9 in ROR1+ leukemia cells of ROR1xTCL1 dTg mice and ROR1Neg leukemia cells from otherwise syngeneic TCL1 Tg mice." (PMID 40295829, 2025). "Cirmtuzumab has currently completed a phase I clinical trial in patients with relapsed or refractory CLL, in which treatment with cirmtuzimab inhibited leukemia-cell activation of Rho-GPTPase and ROR1 signaling." (PMID 38296962, 2024). "Clinical studies have demonstrated that the humanized anti-ROR1 mAb zilovertamab is safe and effective in inhibiting ROR1-signaling in patients with ROR1-positive leukemia." (PMID 38408999, 2024). "Zilovertamab (formerly known as cirmtuzumab or UC‐961) is a monoclonal antibody to ROR1 and is in clinical trials for the treatment of leukaemias and other cancers, such as prostate cancer and lung cancer." (PMID 38689429, 2024). "In conclusion, ROR1 shows a heterogeneous tumour cell expression profile across multiple leukaemias and lymphomas, making it a tumour target that would require different patient selection strategies to develop novel therapeutic modalities." (PMID 39495778, 2024). "Abnormal ROR1 expression appears in many malignant tumors and is related to Rho‐GTPase activation; high ROR1 expression level in leukemia cells is related to poor prognosis." (PMID 38180276, 2024). "A phase 1 trial of zilovertamab in patients with chronic lymphocytic leukemia (CLL) found this mAb was well tolerated and effective in inhibiting ROR1-signaling and cancer-stemness gene expression in leukemia cells of treated patients." (PMID 38408999, 2024). "CAR T cell therapies targeting ROR1 are also gaining interest in tumors that overexpress ROR1, such as leukemias, lymphomas and solid tumors." (PMID 39551787, 2024). "Malignancies such as leukemia, lymphoma, and some solid tumors overexpress ROR1, making it a promising target for cancer treatment." (PMID 36873868, 2023). "Collectively, these results indicate that expression of ROR1 can enhance the viability of the venetoclax-treated leukemia cells, including leukemia cells that expressed mutant forms of BCL2 associated with venetoclax resistance." (PMID 35418613, 2022). "Relevant in this regard is the leukemia-cell expression of the receptor tyrosine kinase-like orphan receptor (ROR1), which can serve as a receptor for Wnt5a." (PMID 35418613, 2022). "In preclinical models of CLL, ROR1 CAR T-cells demonstrated selective toxicity for ROR1 expressing leukemia cells, with rapid clearance of leukemia cells in vivo." (PMID 35406490, 2022). "ROR1 expression on patient’s leukemia cells remains relatively stable throughout the course of their disease, and it not expressed on normal healthy differentiated tissue." (PMID 35406490, 2022). "As both Wnt5a and ROR1 are highly expressed in patients with leukemia, this process can be inhibited by Cirmtuzumab, a monoclonal antibody specific for the extracellular domain of ROR1." (PMID 36250020, 2022). "The CLL cells from over 90% of all patients express ROR1; however, there is heterogeneity in the expression levels of ROR1 on leukemia cells among different patients." (PMID 35418613, 2022).
leukemia (continued). "ROR1 encodes an oncoembryonic surface protein expressed on the CLL cells of over 90% of patients, and ROR1 is a receptor for Wnt5a that promotes leukemia cell proliferation and survival." (PMID 34722255, 2021). "These B-ALL cells are sensitive to siRNA-mediated ROR1 silencing, indicating a critical function of ROR1 to maintain leukemia-cell survival." (PMID 34123850, 2021). "Binding of mAbs to the extracellular domains of ROR1 led to rapid dephosphorylation before leukemia-cell apoptosis." (PMID 34123850, 2021). "In contrast to CD19, the first clinically approved molecule for CAR T cells, which is present on the cell surface of CD19-positive lymphoma and leukemia, the orphan receptor ROR1 is expressed on many epithelial tumors and is also a target for CAR T cells." (PMID 34210970, 2021). "Studies have reported that ROR1 is expressed at a high level in human leukemia and several solid malignancies, suggesting that detection of ROR1 as a prognostic biomarker is important for the on time clinical analysis and the long-term treatment monitoring." (PMID 34290319, 2021). "This is notable as Wnt5a is an identified ligand for ROR1, an evolutionarily conserved and developmentally-restricted type-I surface protein, which is expressed by the leukemia cells of most patients with CLL." (PMID 33097837, 2021). "We examined primary neoplastic cells of patients with MCL who had circulating leukemia cells for Wnt5a-induced, ROR1-dependent activation of Rac1." (PMID 29872501, 2018). "High ROR1 expression on cell membrane in human malignancies enables it to be a therapeutic target for both leukemia and some solid tumors." (PMID 28427197, 2017). "Wnt5a acts as a potential ligand for Ror1 and Ror22, 12, 13 and interaction between Ror1 and Ror2 is required for Wnt5a signaling, which promotes leukemia chemotaxis and proliferation." (PMID 28432357, 2017). "In summary, ROR1-specific CAR+ T cells can efficiently treat ROR1+ leukemia in mice which supports testing of these T cells in the clinic as an investigational therapy for patients with ROR1+ malignancies." (PMID 26030772, 2015). "In order to evaluate the anti-tumor activity of ROR1-specific CAR+ T cells in vivo, a xenograft model of leukemia was established in immunocompromised mice and treated with ROR1-specific CAR+ T cells." (PMID 26030772, 2015). "A truncated ROR1 has been described in fetal CNS tissues, adult human CNS tumors, leukemia/lymphoma cell lines and in a variety of human cell lines of neuroectodermal origin using northern blot analyses." (PMID 24205204, 2013). "A truncated ROR1 gene has been found in the fetal and adult human central nervous system, in human leukemia and lymphoma cell-lines and in a variety of human cancer derived from the neuroectoderm with a predicted protein size of 40 kDa." (PMID 24205204, 2013). "In prior studies, we and others found that ROR1 was expressed by leukemia cells and some cancer cell lines, and was involved in cell survival." (PMID 22403610, 2012). "While the clinical translation of ROR1-targeted therapies for solid tumors remains in early development, its success in hematological malignancies, such as leukemia, has provided critical information for its potential application for more challenging solid tumor types." (PMID 39849645, 2025). "To compare ROR1 prevalence across these investigated leukaemias and lymphomas, we computed ROR1 positivity from each indication as positive or negative, which was the only common parameter that could be identified from both IHC and FC analysis." (PMID 39495778, 2024). "In addition, MSCs interfered with the secretory potential of leukemia-associated WT1- and ROR1-targeting CTL clones, inhibiting the release of IFNγ, tumor necrosis factor alpha, and IL-2." (PMID 38231344, 2024).